SENP1 (SUMO specific peptidase 1)
Diseases named in the same sentence as SENP1 in open-access papers (continued):
Sharing a sentence is not in itself a finding about the gene and the disease.
colon cancer (16 papers, 2013 to 2025). "Similar results have also been observed in analyses of other solid cancer types, including cancers of the colon, bladder, head & neck, and lung, where SENP1 overexpression was consistently linked to advanced and high-grade cancers and in some studies also with adverse clinical outcome." (PMID 26202067, 2015). "In colon cancer, research indicated that SENP1 diminished the phase separation of RNF168, thereby enhancing DNA damage repair and contributing to drug resistance." (PMID 41567198, 2025). "SENP1 is overexpressed in colon cancer (COAD) and silencing of SENP1 inhibits cell proliferation through upregulating CDK inhibitors including p21 and p27." (PMID 37415251, 2023). "In recent years, it has been found that SENP1 is highly expressed in prostate, pancreatic and colon cancer, and knockout of SENP1 greatly affects the biological function of these tumors." (PMID 33791211, 2021). "We previously revealed that SENP1 promotes prostate tumor growth and metastasis, and is overexpressed in most colon cancer tissues and essential for colon cancer cell growth." (PMID 27741516, 2016). "They reported that SENP1 overexpressed in most of the colon cancer tissues and its silencing arrested the cell growth in nude mice and the colony formation in a colon cancer cell line DLD-1." (PMID 25893082, 2015). "Moreover, c-MYC and JAK2 were identified as targets of SENP1 in colon cancer, indicating the promising potential of SENP1 for cancer therapy." (PMID 38954215, 2025). "It was found that SENP1 was overexpressed in colon cancer tissues, and silencing SENP1 expression could inhibit the growth of colon cancer cells by arresting the cells in G1 phase." (PMID 37777749, 2023). "SENP1 was also over expressed in most of colon cancer tissues." (PMID 27178176, 2016). "Consequently, overexpression of SENP1 has been found in various cancer types, such as colon cancer, bladder cancer, head & neck cancer, and lung cancer, and has been linked to poor clinical features in some of these." (PMID 26202067, 2015). "Results of experiments with siRNA to inhibit SENP1 expression in DLD-1 colon cancer cell line, suggest a potential role for SENP1 in colon cancer cell proliferation, tumor formation and cell cycle progression." (PMID 27178176, 2016).
lung carcinoma (12 papers, 2013 to 2026). "The underlying mechanisms that may have caused the SENP1 depletion to increase the radiosensitivity of lung cancer cells were investigated." (PMID 24137315, 2013). "Inhibiting SENP1 can effectively suppress the growth of lung cancer cells by activating A20-mediated ferroptosis." (PMID 37670258, 2023). "Another study found that inhibiting SENP1 significantly increases the radiosensitivity of lung carcinoma by promoting ionizing radiation-induced cell cycle arrest, γ-Histone H2A family member X (γ-H2AX) expression, and apoptosis." (PMID 37670258, 2023). "The overexpression of SENP1 contributed to chemoradiotherapy resistance in non‐small cell lung cancer." (PMID 33686713, 2021). "Upregulation of miR-138 enhanced radiosensitivity of lung cancer cells by inhibiting SENP1 and increasing apoptosis." (PMID 27075472, 2016). "SENP1 was observed to be overexpressed in lung cancer tissues, and the modulation of SENP1 expression was demonstrated to significantly affect the proliferation of lung cancer cells." (PMID 24137315, 2013). "Western blot analysis with an anti-SENP1 antibody was then employed to examine the SENP1 protein expression in clinical samples, including five primary lung cancer samples and their adjacent normal tissues." (PMID 24137315, 2013). "The results of the study showed that the inhibition of SENP1 markedly enhanced the radiosensitivity of lung carcinoma by promoting IR-induced cell cycle arrest, γ-H2AX expression and apoptosis." (PMID 24137315, 2013). "It was shown that SENP1 depletion significantly sensitized lung cancer cells to IR and that SENP1 depletion enhanced IR-induced lung cancer cell cycle arrest at the G0/G1 stage." (PMID 24137315, 2013). "Aberrantly increased SENP1 expression predicts a poor prognosis in patients with lung cancer." (PMID 38072908, 2023). "Inhibition of SENP1 inhibits the proliferation and growth of lung cancer cells." (PMID 38072908, 2023). "Following this, the ability of SENP1 inhibition to affect lung cancer radioresistance was examined." (PMID 24137315, 2013). "The aim of this study was to identify whether small ubiquitin-related modifier (SUMO)-specific protease 1 (SENP1) is a marker of radioresistance that may serve as a target for enhancing the efficacy of lung carcinoma radiotherapy." (PMID 24137315, 2013). "Furthermore, the ability of SENP1 inhibition to increase IR-induced lung cancer cell apoptosis was investigated." (PMID 24137315, 2013). "In the present study, it was demonstrated that SENP1 may be a regulator of lung cancer radioresistance." (PMID 24137315, 2013). "The results showed that SENP1 was overexpressed in the lung cancer samples." (PMID 24137315, 2013). "In the present study, it was identified that SENP1 was also overexpressed in lung cancer." (PMID 24137315, 2013). "Recently, specific inhibitors of SENP1 have been designed, and there is consequently a requirement to investigate whether these inhibitors enhance the radiosensitivity of lung carcinoma." (PMID 24137315, 2013). "Moreover, silencing the expression of SENP1 using small interfering RNA (siRNA) significantly sensitized lung cancer cells to radiation." (PMID 24137315, 2013). "In addition, we further discovered that hypoxia could enhance Slug SUMOylation through disrupting the interaction between Slug and SENP1/2, and result in lung cancer malignancy." (PMID 30612578, 2019). "SENP1-siRNA-transfected cells treated with IR showed the highest protein level of γ-H2AX, suggesting that increased γ-H2AX expression may be one of the underlying mechanisms responsible for the increase in the radiosensitivity of lung cancer cells when SENP1 is inhibited." (PMID 24137315, 2013). "However, silencing the expression of SENP1 enhanced IR-induced lung cancer cell apoptosis and caspase 3 activation, which may have contributed to the IR-induced lung cancer cell sensitivity." (PMID 24137315, 2013).
lung carcinoma (continued). "Furthermore, identical experiments were performed using H460 cells, which provided similar results to those in the A549 cell line, indicating that SENP1 depletion may increase the radiosensitivity of lung cancer cells." (PMID 24137315, 2013). "Studies have shown that SENP1 can modulate the inflammatory signal A20, which interacts with ACSL4 and SLC7A11 to regulate ferroptosis in lung cancer cells." (PMID 36639654, 2023). "The results showed that SENP1 mRNA and protein was significantly overexpressed in lung cancer tissues when compared with their adjacent non-tumor lung tissues." (PMID 24137315, 2013). "SENP1 had been reported to overexpressed in patients with lung cancer, and had a negative correlation with treatment response and could potentially predict chemosensitivity." (PMID 39211047, 2024). "Notably, SENP1 inhibition did not result in lung cancer cell apoptosis, as demonstrated by fluorescence-activated cell sorting (FACS) assay and the caspase 3 activation assay." (PMID 24137315, 2013).
osteosarcoma (11 papers, 2021 to 2025). A usually aggressive malignant bone-forming mesenchymal neoplasm, predominantly affecting adolescents and young adults. "Another study suggests that plasma exosome-derived SENP1 associates with higher tumor diameter and tumor stage in patients with osteosarcoma." (PMID 35782332, 2021). "However, another study has associated SENP1 overexpression with increased sensitivity to chemotherapy in osteosarcoma, as well as to reduced stemness and HIF-1α down-regulation." (PMID 38534381, 2024). "SENP1 levels were elevated in osteosarcoma patients and correlated with clinical features like tumor size, stage, and metastasis." (PMID 40303340, 2025). "SENP1 shows strong prognostic value in osteosarcoma (AUROC: 0.90 for 1-year, 0.96 for 3-year survival)." (PMID 40303340, 2025). "In osteosarcoma, overexpressed SENP1 decreases the expression of apoptotic protein BCL2-Associated X (BAX) while upregulates Bcl-2, consequently preventing cell apoptosis." (PMID 38389923, 2024). "Consistently, SENP1 at a higher level has been found to be a poor prognostic marker in osteosarcoma patients." (PMID 38534381, 2024). "Researchers also found that SENP1 knockdown suppressed the invasive ability of osteosarcoma cells through modulating EMT marked genes." (PMID 38389923, 2024). "Wang and colleagues elucidated a potential role of SENP1 in osteosarcoma development and invasiveness by the observation that a positive feedback loop exists between HIF-1α and SENP1." (PMID 35465332, 2022). "Low SENP1 is essential for maintaining the stemness of osteosarcoma stem cells, and overexpression of SENP1 markedly decreases the stemness of osteosarcoma cells while sensitizing them to apoptosis induced by HSV-TK/GCV combination treatment." (PMID 36078118, 2022). "In this study, we investigated plasma exosome-derived sentrin SUMO-specific protease 1 (SENP1) levels as a prognostic biomarker in patients with osteosarcoma." (PMID 33791211, 2021). "ELISA was used to detect plasma exosome-derived SENP1 levels to assess prognosis in patients with osteosarcoma." (PMID 33791211, 2021). "In summary, our study revealed that osteosarcoma patients with higher plasma exosome-derived SENP1 levels had worse DFS and OS." (PMID 33791211, 2021). "The expression of SENP1 protein in osteosarcoma tissues and adjacent tissues was detected by immunohistochemistry (IHC)." (PMID 33791211, 2021). "To date, this is the first study to examine the potential of plasma exosome-derived SENP1 in osteosarcoma diagnosis." (PMID 33791211, 2021). "In recent years, several studies have reported that SENP1 is highly expressed in prostatic and pancreatic cancer and osteosarcoma, and knockout of SENP1 affects the biological function of these tumors." (PMID 34422639, 2021). "SENP1 promotes proliferation, invasion, and epithelial–mesenchymal transition of osteosarcoma cells by regulating HIF-1α expression under hypoxia." (PMID 33791211, 2021). "Firstly, although this was the largest study to date evaluating SENP1 protein expression in osteosarcoma, detection of gene levels is necessary to confirm the findings." (PMID 33791211, 2021). "Secondly, the application of plasma exosome-derived SENP1 levels as a clinical prognostic biomarker in patients with osteosarcoma needs to be confirmed and validated with a large multicenter sample." (PMID 33791211, 2021). "One study aims at determining the ability of a novel SENP1 inhibitor, senpPNA-R8, to silence SENP1 expression and penetrate into organotypic osteosarcoma cultures prepared from freshly collected patient samples (NCT03798587)." (PMID 34503213, 2021). "We assessed the correlations between plasma exosome-derived SENP1 levels and tumor characteristics in patients with osteosarcoma." (PMID 33791211, 2021). "The positive expression rate of SENP1 in osteosarcoma tissues was 88.33% (53/60), whereas that in adjacent tissues was 46.67% (28/60) (P < 0.05)." (PMID 33791211, 2021).
osteosarcoma (continued). "In order to study the role of plasma exosome-derived SENP1 in patients with osteosarcoma, we extracted exosomes from the plasma of patients with osteosarcoma." (PMID 33791211, 2021). "IHC showed that the positive expression rate of SENP1 in osteosarcoma tissues was 88.33%, whereas that in adjacent tissues was 46.67% (P < 0.05)." (PMID 33791211, 2021). "Plasma exosome-derived SENP1 is a potential prognostic biomarker in osteosarcoma." (PMID 38389923, 2024). "Notably, the prognostic value of plasma exosome-derived SENP1 levels in osteosarcoma was found to be better than plasma SENP1." (PMID 36078118, 2022). "SENP1/HIF-1alpha regulates hypoxia-mediated EMT in osteosarcoma cells." (PMID 35836470, 2022). "This highlights the potential for using SENP1 activation for the treatment of osteosarcoma." (PMID 36078118, 2022). "SENP1 expression has also been detected in osteosarcoma cells." (PMID 33791211, 2021). "The expression of SENP1 in osteosarcoma and adjacent tissues was evaluated by IHC." (PMID 33791211, 2021). "The prognostic value of plasma exosome-derived SENP1 levels in osteosarcoma." (PMID 33791211, 2021). "Hence, in this study we investigated the prognostic value of SENP1 in patients with osteosarcoma by determining the concentration of plasma exosomes from patients." (PMID 33791211, 2021). "Correlations between plasma exosome-derived SENP1 levels and tumor characteristics in patients with osteosarcoma were assessed, which showed that the plasma exosome-derived SENP1 levels were related to tumor size, tumor location, necrosis rate, pulmonary metastasis, and surgical stage." (PMID 33791211, 2021). "SENP1 expression in osteosarcoma tissues was significantly higher than in adjacent tissues." (PMID 33791211, 2021). "Therefore, further studies on SENP1 are necessary to clarify its role in osteosarcoma." (PMID 38534381, 2024). "In the human osteosarcoma cell line MG-63, a hypoxic environment (similar to that typically found in tumors) induces the expression of high amounts of SENP1, and inhibiting SENP1, in turn, reduces the expression of two major hypoxia-induced genes, HIF1α and VEGF (vascular endothelial growth factor)." (PMID 36078118, 2022). "Finally, we assessed the prognostic value of plasma exosome-derived SENP1 levels in osteosarcoma." (PMID 33791211, 2021). "The involvement of SENP1/HIF-1α axis in the regulation of cell viability, EMT and invasion under hypoxia shed a light on its role as potential therapeutic target for osteosarcoma treatment." (PMID 35465332, 2022). "However, the expression and prognostic value of SENP1 in patients with osteosarcoma remain unclear." (PMID 33791211, 2021). "Concerning the association of SENP1 expression with prognosis in patients with cancer, higher plasma exosome-derived SENP1 correlates with worse DFS and OS in patients with osteosarcoma; additionally, SENP1 overexpression independently correlates with poor prognosis in patients with NSCLC." (PMID 35782332, 2021). "Among all patients with osteosarcoma, both DFS and OS were worse in patients who had higher plasma exosome-derived SENP1 levels compared with those in patients with lower plasma exosome-derived SENP1 levels (P < 0.001)." (PMID 33791211, 2021). "Thirdly, we did not perform an assessment of the mechanisms of SENP1 function, including up- and downstream genes in osteosarcoma." (PMID 33791211, 2021). "In addition, SENP1 expression is decreased in osteosarcoma tissues, cell lines, and osteosarcoma stem cells compared to non-cancer cells and stem cells." (PMID 36078118, 2022).
ovarian carcinoma (9 papers, 2015 to 2025). A malignant neoplasm originating from the surface ovarian epithelium. "To explore the application of anti-SENP1/JAK2 for treatment of platinum-resistant ovarian cancer, we found SENP1 deficiency or treatment by SENP1 inhibitor Momordin Ic significantly overcomes platinum-resistance of ovarian cancer." (PMID 33795649, 2021). "Using Mc or SENP1 siRNA to inhibit SENP1 shows a strong synergistic effect with cisplatin in treating platinum-resistant ovarian cancer." (PMID 41303693, 2025). "Targeting SENP1 through genetic targeting or using Momordin Ic significantly overcame platinum resistance in ovarian cancer." (PMID 39859203, 2025). "The high expression of SENP1 is significantly correlated with an adverse prognosis in various cancers, including ovarian cancer, osteosarcoma, and colorectal cancer." (PMID 41303693, 2025). "The SENP1/JAK2 pathway is active in cisplatin-resistant ovarian cancer and is dependent on the transcription factor RUNX2." (PMID 41303693, 2025). "This study provides with a potential application of SENP1 inhibitors for the treatment of platinum-resistant ovarian cancer patients." (PMID 33795649, 2021). "Together our results suggest that inhibition of SENP1 is a promising therapeutic approach to overcome platinum-resistance in ovarian cancer." (PMID 33795649, 2021). "While we observed higher expression of SENP1 total protein in the normal tissues of ovarian cancer and UCEC (Uterine corpus endometrial carcinoma) compared with primary cancer tissues." (PMID 34276383, 2021). "Together, these results suggest that RUNX2 is a critical transcription factor regulating SENP1 expression in platinum-resistant ovarian cancer." (PMID 33795649, 2021). "In this study, for the first time, we discovered that SENP1 directly regulates JAK2 cellular localization via deSUMOylation, and activated SENP1/JAK2 signaling is critical for platinum-resistance in ovarian cancer." (PMID 33795649, 2021). "Our study for the first time revealed that a transcription factor RUNX2 is responsible for the increased SENP1 mRNA level in cisplatin-resistant ovarian cancer cells." (PMID 33795649, 2021). "To further confirm the role of SENP1 in platinum-resistance of ovarian cancer patients, we measured SENP1 mRNA expression levels from tumor samples of 61 platinum-sensitive patients and 32 platinum-resistant patients." (PMID 33795649, 2021). "Consistently, the protein levels of SENP1 were also upregulated in platinum-resistant ovarian cancer cells, in which SUMOylation of JAK2 was decreased correspondingly." (PMID 33795649, 2021). "This novel SENP-1-mediated mechanism encouraged us to found that SENP1 knockdown or inhibition overcomes cisplatin-resistance in ovarian cancer." (PMID 33795649, 2021). "Our clinical studies demonstrated that SENP1/JAK2 signaling is activated in tumors from platinum-resistant ovarian cancer patients." (PMID 33795649, 2021). "Taken together, our study warrantee further investigation to define the mechanisms by which SENP1-SUMO mediates BMP4 gene expression, which will provide potential therapeutic targets for human POI and other ovarian associated diseases such as ovarian cancer." (PMID 28770041, 2017). "In the present study, we for the first time confirmed that SENP1 inhibition can sensitize ovarian cancer cells to cisplatin in hypoxia by inhibiting HIF-1α." (PMID 26548925, 2015). "In this study, we examined the expression of HIF-1α protein in ovarian cancer cells of SKOV3 by inhibiting or up-regulating SENP1 and found that SENP1 stabilized HIF-1α protein in hypoxia through desumoylation." (PMID 26548925, 2015). "The data suggested that pomolic acid and tormentic acid may be promising compounds for in vivo studies of platinum-resistant ovarian cancer with SENP1 activation." (PMID 41303693, 2025). "SENP1 was chosen due to its involvement in different pathways, and it may have a role in responses to chemotherapy in ovarian cancer." (PMID 39859203, 2025).